SIRT3 (sirtuin 3)
Diseases named in the same sentence as SIRT3 in open-access papers (continued):
Sharing a sentence is not in itself a finding about the gene and the disease.
non-small cell lung carcinoma (12 papers, 2016 to 2026). A group of at least three distinct histological types of lung cancer, including non-small cell squamous cell carcinoma, adenocarcinoma, and large cell carcinoma. "It was discovered through research into the impact of miR-224 on the growth of non-small cell lung cancer induced by cancer-associated fibroblast (NSCLC) that overexpression of SIRT3 can suppress miR-224 by activating AMPK and deactivating mTOR/HIF-1α." (PMID 37175631, 2023). "Recent research indicated that high expression of miR-224 in CAFs facilitated proliferation, EMT and metastasis of non-small cell lung cancer cells by the SIRT3/AMPK/mTOR/ HIF1α signaling pathway." (PMID 35589690, 2022). "In non-small cell lung cancer, SIRT3 promotes the oncogenic role of NMNAT2 to stimulate cancer cell proliferation." (PMID 32724473, 2020). "Recent studies also indicated that the function of NMNAT2 is partially overlapped with SIRT3, which improves mitochondrial functions, and is related to energy metabolism in human non-small cell lung carcinoma (NSCLC) cell lines A549." (PMID 27218101, 2016). "SIRT3 activates NMNAT2 through deacetylation and increases NAD+ levels in non-small cell lung cancer cells." (PMID 34445574, 2021).
cognitive decline (11 papers, 2018 to 2024). "SIRT3 is a crucial antioxidant enzyme that mitigates cognitive decline associated with anesthesia and surgery by suppressing mitochondrial oxidative stress and neuroinflammation." (PMID 39533332, 2024). "This suggests that SIRT3 upregulation can reverse brain oxidative stress, which is implicated in cognitive decline." (PMID 33541361, 2021). "SIRT3 deficiency-induced mitochondrial dysfunction and neuroinflammation in MetS could be causes of cognitive decline." (PMID 33806509, 2021). "Activating SIRT3 regulation of mitochondrial dysfunction and neuroinflammation leads to ameliorating cognitive decline in mice." (PMID 36918872, 2023). "Overall, these data imply that SAL can ameliorate cognitive decline in AD mice, which is dependent on SIRT3 expression." (PMID 36333711, 2022). "Collectively, these results indicated that SIRT3 overexpression attenuated anesthesia/surgery-induced hippocampus-dependent cognitive decline in aged mice." (PMID 33541361, 2021). "The purpose of the current study was to assess the effect of SIRT3 in anesthesia/surgery-induced cognitive decline in aged mice with hippocampal inflammation-related molecular mechanisms." (PMID 33541361, 2021). "SIRT3 protects against cognitive decline, mitochondrial dysfunction and oxidative stress, and improves mood and cognition." (PMID 33806509, 2021). "Surprisingly, Honokiol can ameliorate surgery-induced or anesthesia-induced cognitive decline in mice via SIRT3 activation mediating ROS elimination and apoptosis inhibition." (PMID 32724473, 2020). "Therefore, we hypothesize that SIRT3 deficiency-mediated mitochondrial dysfunction leads to inflammasome formation in the brain of MetS and thereby setting the stage for chronic CNS inflammation, one of the causes of cognitive decline." (PMID 30510203, 2018). "Another study in aged mice showed that SIRT3 overexpression can provide protection against anesthesia/surgery-induced synaptic plasticity dysfunction in the hippocampus and attenuate hippocampus-dependent cognitive decline." (PMID 37960975, 2023). "In particular, autophagy may be restored by PACAP, reversing cognitive decline in AD; Sirt3 downregulation would reduce the therapeutic effect of PACAP." (PMID 37891608, 2023). "In addition, SIRT3 overexpression prevented anesthesia/surgery-induced cognitive decline and synaptic plasticity dysfunction in aged mice." (PMID 33541361, 2021). "In conclusion, the current study indicated that SIRT3 may attenuate postoperative cognitive decline by preventing the anesthesia/surgery-induced neuroinflammatory response in the hippocampal CA1 region of aged mice." (PMID 33541361, 2021).
leukemia (11 papers, 2012 to 2024). A malignant (clonal) hematologic disorder, involving hematopoietic stem cells and characterized by the presence of primitive or atypical myeloid or lymphoid cells in the bone marrow and the blood. "Recent studies have shown that ABZ-induced SIRT3 suppression causes the generation of mitochondrial ROS, which subsequently elicits apoptosis in leukemia cells." (PMID 32486166, 2020). "In leukemia cells, increasing SIRT3 contributed to apoptosis caused by Kaempferol treatment." (PMID 23272146, 2012). "SIRT3, a key mitochondrial deacetylase, has been revealed to be a potential therapeutic target for the treatment of leukemia." (PMID 35433629, 2022). "In conclusion, a potent SIRT3 selective inhibitor (P6) was discovered with in vitro MLLr leukemia inhibitory activity." (PMID 35433629, 2022). "In this study, we report that contrary to what has been known in solid tumors, in K562 human leukemia cells, Sirt3 plays an opposite role in relieving oxidative stress." (PMID 27232755, 2016). "Besides, SIRT3 facilitates the survival and function of leukemia stem cells in acute myeloid leukemia by regulating fatty acid oxidation essential for OXPHOS and ATP production in leukemia stem cells." (PMID 38773972, 2024). "Basal but not enhanced autophagy activity maintains ubiquitination-proteasomal degradation of Sirt3 to limit ROS level, representing an adaptive mechanism by which autophagy, in collaboration with ubiquitination-proteasomal system, buffers oxidative stress in the leukemia cells." (PMID 27232755, 2016). "The general results of leukemia have shown that: (i) SIRT2 and SIRT3 can be considered as important prognostic markers for the disease, (ii) in ALL, SIRT2 participates in processes such as tumor growth and (iii) in CLL, SIRT3 acts in the control of reactive oxygen species." (PMID 36230534, 2022). "Additionally, we screened their effect on the enzymatic activity of the histone deacetylase sirtuin family (SIRT1, SIRT2, SIRT3, SIRT5 and SIRT6) using both recombinant enzymes and nuclear lysates from leukemia cells." (PMID 32587297, 2020). "To examine whether SIRT3 also inhibited the cytotoxic effect of ABZ-induced MCL1 suppression in other cell lines, we analyzed the cytotoxicity of ABZ on human leukemia MEG-01 cells." (PMID 32486166, 2020).
age-related hearing loss (10 papers, 2013 to 2023). "SIRT3, located to mitochondria, has been implicated in counteracting age-related hearing loss and noise-induced damage." (PMID 36912880, 2023). "NR supplementation in rodents has also been reported to improve noise-induced and age-related hearing loss via SIRT3 activation." (PMID 35927255, 2022). "Furthermore, decreases in SIRT3 have been associated with age-related hearing loss and age-exacerbated heart damage." (PMID 31956305, 2019). "Interestingly, SIRT3 activity has been shown to delay the onset of age-related hearing loss and protect hair cells from both noise and aminoglycoside-induced hair cell damage due to its role in antioxidant defense." (PMID 30596476, 2018). "Although SIRT3 is essential in the prevention of age-related hearing loss, there is no data on the role of SIRT3 in mediating the cardioprotective effects of CR." (PMID 30131726, 2018). "In a study of age-related hearing loss, mice lacking Sirt3 (Sirt3–/–) significantly lose their protective role against oxidative damage compared to wild-type mice, manifesting that Sirt3-mediated mitochondrial oxygen metabolism may be a pivotal regulatory mechanism of aging retardation." (PMID 33330487, 2020).
diffuse large B-cell lymphoma (10 papers, 2019 to 2025). "Reduced ATF4 translation was previously observed in SIRT3-deficient diffuse large B-cell lymphoma cells." (PMID 38395990, 2024). "On the one hand, SIRT3 knockout leads to disordered glutamine metabolism and induces autophagy-dependent cell death in diffuse large B-cell lymphoma (DLBCL)." (PMID 40943150, 2025). "Diffuse large B cell lymphomas (DLBCLs) are dependent on SIRT3 for proliferation, survival, self-renewal, and tumor growth in vivo." (PMID 39372420, 2024). "We show that ATM deficiency in diffuse large B-cell lymphoma (DLBCL) significantly induce mitochondrial deacetylase sirtuin-3 (SIRT3) activity, disrupted mitochondrial structure, decreased mitochondrial respiration, and compromised TCA flux compared with DLBCL cells expressing wild type (WT)-ATM." (PMID 33273545, 2020). "Also, SIRT3 highly expressed in Diffuse large B cell lymphomas (DLBCLs), which are dependent on mitochondrial lysine deacetylase SIRT3 for proliferation, survival, self-renewal, and tumor growth." (PMID 33273692, 2020). "Diffuse large B-cell lymphomas (DLBCL) are broadly dependent on anaplerotic metabolism regulated by mitochondrial SIRT3." (PMID 35019856, 2022). "YC8-02 inhibits the TCA cycle in Diffuse large B cell lymphomas (DLBCL) by preventing the decrease of glutamate dehydrogenase and acetyl-CoA through SIRT3, leading to autophagic cell death and suppression of DLBCL cell proliferation." (PMID 38773972, 2024).
esophageal cancer (10 papers, 2015 to 2025). A primary or metastatic malignant neoplasm involving the esophagus. "High expression of SIRT3 is associated with shorter survival time in esophageal cancer patients." (PMID 27367026, 2016). "Alternatively, other cancers, such as esophageal cancer and oral squamous cell carcinoma, SIRT3 promotes tumor growth." (PMID 39501597, 2024). "The 5‐year postoperational survival rate of patients with esophageal cancer was examined in relation with the SIRT3 expression." (PMID 27686535, 2017). "Accordingly, high expression of SIRT3 was related to a shorter survival time in patients with esophageal cancer, which might be due to the suppression of apoptosis signals that prolonged the survival rate of esophageal cancer." (PMID 27686535, 2017).
sarcopenia (10 papers, 2019 to 2025). Progressive decline in muscle mass due to aging which results in decreased functional capacity of muscles. "The age-related decrease in SIRT1 and SIRT3 levels is linked to the development of sarcopenia and age-related muscle dysfunction." (PMID 38004107, 2023). "Aging results in muscle mass loss (sarcopenia), decreased mitochondrial respiration, lower SIRT3 and PGC-1α levels and decreased muscle performance, which promotes increases frailty and morbidity." (PMID 34829803, 2021). "In human aging, sedentariness is associated with SIRT3 expression reduction in skeletal muscle with consequent sarcopenia in the elderly population, but PA enhances SIRT3 expression and eliminates differences between young and older individuals." (PMID 31557786, 2019). "The next analyzed gene in this study, which seems important for understanding sarcopenia’s pathogenesis, is SIRT3." (PMID 40034697, 2025). "Aging individuals are also less physically active; sedentarism induces muscle atrophy and reduces mitochondrial mass and biogenesis regulators (SIRT3 and PGC-1α) in human muscle cells, which further predisposes the individuals to sarcopenia." (PMID 34829803, 2021). "Thus, HSF1 regulates skeletal muscle functions and systemic energy homeostasis via the SIRT3-PGC1α axis, representing a potential therapeutic target for sarcopenia and metabolic disorders." (PMID 41400028, 2025). "In addition, it provides experimental evidence that vitamin D has the potential to be developed as a therapeutic or preventive agent against sarcopenia through the stimulation of the VDR/SIRT1/SIRT3 axis." (PMID 38004107, 2023). "However, it is certain that novel modulators targeting SIRT1 and SIRT3 will be explored in the near future, which requires further unravelling the molecular pathway involved in frailty and its component sarcopenia." (PMID 36818553, 2023). "We speculated that SIRT3 may be a promising therapeutic target for sarcopenia." (PMID 41156549, 2025). "Hence, SIRT3 might be an important therapeutic target for treating sarcopenia." (PMID 41156549, 2025). "The hypothesis is that genes involved in epigenetic modifications, such as SIRT1, SIRT3, SIRT6, FOXO1, FOXO3A, DNMT3A, and ELAVL1, are critical for the development of sarcopenia and could be used as biomarkers for the diagnosis and monitoring of the disease." (PMID 40034697, 2025). "Furthermore, we observed increased expression of SIRT3, SIRT6, FOXO1, and ELAVL1 in patients with sarcopenia compared to the geriatric controls and the frailty group, although these differencesdid not reach statistical significance." (PMID 40034697, 2025). "In patients suffering from sarcopenia, FOXO3A mRNA level did not correlate with other analyzed genes, while in the geriatric control group, FOXO3A expression correlated with the SIRT genes (SIRT1 r=0.56, p=0.004; SIRT3 r=0.48, p = 0.015; and SIRT6 r=0.58, p=0.002)." (PMID 40034697, 2025).
acute myeloid leukemia (9 papers, 2020 to 2025). Acute myeloid leukemia (AML) is a group of neoplasms arising from precursor cells committed to the myeloid cell-line differentiation. "Sirtuin 3 (SIRT3) deacetylase is a key regulator of chemoresistance in acute myeloid leukemia (AML) cells." (PMID 41303693, 2025). "Meanwhile, studies have also shown that SIRT3 promotes the chemical resistance of acute myelocytic leukemia (AML) by regulating mitochondrial metabolism." (PMID 35906622, 2022). "Previous studies have suggested that the blocking of SIRT3 activity can be utilized to improve the anti-leukemic efficacy of standard chemotherapeutic agents for acute myeloid leukemia." (PMID 32486166, 2020). "It was recently shown that SIRT3 promotes therapeutic resistance in acute myeloid leukemia by reprograming mitochondrial metabolism towards OxPhos and by downregulating ROS generation." (PMID 33273545, 2020). "SENP1 activates sirtuin 3 (SIRT3) by preventing its proteasome degradation through which exacerbates resistance against chemotherapy in acute myeloid leukemia (AML) cells." (PMID 38389923, 2024). "Sirtuin 3 (SIRT3) deacetylase is a key regulator for chemoresistance in acute myeloid leukemia (AML) cells due to its capability of modulating mitochondrial metabolism and reactive oxygen species (ROS)." (PMID 35955415, 2022). "It is reported that overexpression of SIRT3 can reprogram mitochondrial metabolism by enhancement of oxidative phosphorylation (OxPhos) and decrease of ROS generation in acute myeloid leukemia (AML) cells." (PMID 35433629, 2022).
bladder carcinoma (9 papers, 2011 to 2024).
chronic lymphocytic leukemia (9 papers, 2019 to 2025). "In contrast, other studies have reported that upregulated SIRT3 expression in chronic lymphocytic leukemia (CLL) cells is associated with tumor cell survival by facilitating the elimination of superoxide anions." (PMID 41154474, 2025). "In chronic lymphocytic leukemia cells, SIRT3 regulates fatty acid oxidation, which is essential for OXPHOS and ATP synthesis, hence promoting cancer cell survival." (PMID 39479446, 2024). "SIRT3 overexpression in chronic lymphocytic leukemia (CLL) prevents ROS overaccumulation and reduces detrimental cytotoxic effects." (PMID 39479446, 2024). "SIRT3 is a deacetylase that localizes to the mitochondria and has been associated with neurodegenerative diseases and the following cancers: B-cell chronic lymphocytic leukemia (CLL), mantle cell lymphoma, breast cancer, and gastric cancer." (PMID 37456463, 2023). "SIRT3 overexpressed in chronic lymphocytic leukemia (CLL) and diffuse large B cell lymphomas (DLBCLs) cells contributes to the proliferation, survival and self-renewal of tumor cells." (PMID 35433629, 2022). "Furthermore, Sirt3 protein expression was reduced in chronic lymphocytic leukemia (CLL) primary samples and in malignant B-cell lines." (PMID 31010244, 2019).
gallbladder cancer (9 papers, 2022 to 2024). "The expression level of SIRT3 in patients with gallbladder cancer (GBC) is notably lower compared to adjacent normal tissues, and low expression of SIRT3 is positively associated with poor overall survival." (PMID 39396974, 2024). "SIRT3 can inhibit AKT-dependent mitochondrial metabolism in gallbladder cancer, thereby inducing ferroptosis and tumor suppression." (PMID 38773972, 2024). "For example, reduced expression of sirtuin 3 (SIRT3) in patients with gallbladder cancer leads to the inhibition of ACSL4 through AKT serine/threonine kinase (AKT/PKB) signaling, in contrast to the normal tissues surrounding the cancer." (PMID 37372148, 2023). "Intriguingly, SIRT3 also plays an opposing role in gallbladder cancer." (PMID 37153222, 2023). "What’s more, Liu L reported that SIRT3, a mitochondrial NAD+-dependent histone deacetylase, led gallbladder cancer cells to ferroptosis, thus to function for EMT inhibition and tumor suppression." (PMID 37787987, 2023). "Sirtuin 3 (SIRT3), an NAD+-dependent histone deacetylase, is down-regulated in gallbladder cancer and correlates with poor overall survival." (PMID 36497375, 2022).
head and neck squamous cell carcinoma (9 papers, 2011 to 2025). A squamous cell carcinoma that arises from any of the following anatomic sites: lip and oral cavity, nasal cavity, paranasal sinuses, pharynx, larynx, and salivary glands. "Consistent with mitochondrial Sirt3 inhibition, LC-0296 increased global mitochondrial protein acetylation, acetylation of the Sirt3 target glutamate dehydrogenase, and reactive oxygen species levels in head and neck squamous cell carcinoma (HNSCC) cell lines." (PMID 38474697, 2024). "LC-0296, a novel SIRT3 inhibitor, can inhibit cell survival and promote apoptosis by increasing ROS levels in head and neck squamous cell carcinoma (HNSCC) cells." (PMID 36815979, 2023). "It was reported that the survival and proliferation of human head and neck squamous cell carcinoma (HNSCC) cells were inhibited by the SIRT3 inhibitor LC-0296, and intracellular ROS and DNA cleavage were observed to be significantly upregulated in LC-0296-treated HNSCC cells." (PMID 36060706, 2022). "For example, in head and neck squamous cell carcinoma (HNSCC), SIRT3 promotes cancer cell proliferation and migration by maintaining ROS levels, thereby driving tumor progression." (PMID 40885386, 2025).